PIPOX (pipecolic acid and sarcosine oxidase)
Description:
Metabolizes sarcosine and L-pipecolic acid.
Synonyms: LPIPOX
Tractability: PROTAC: its protein half-life has been measured.
Target class: Enzyme; Oxidoreductase
Gene: Protein-coding gene on chromosome 17 (28,950,513 to 29,057,583, forward strand). Ensembl gene ENSG00000179761.
Subcellular location: Peroxisome
Pathways (Reactome):
Metabolism: Lysine catabolism
Protein localization: Peroxisomal protein import
Gene Ontology:
Molecular function: L-pipecolate oxidase activity; protein binding; sarcosine oxidase activity; flavin adenine dinucleotide binding; oxidoreductase activity; oxidoreductase activity, acting on the CH-NH group of donors, oxygen as acceptor
Biological process: L-lysine catabolic process; amino acid catabolic process
Cellular component: peroxisome; cytosol; peroxisomal matrix
Genetic constraint (gnomAD): Loss-of-function variants: 41 observed, 48.02 expected, observed/expected ratio (o/e) 0.85, 90% interval 0.66 to 1.11. The upper end of that interval is the gene's LOEUF score, 1.11, which puts it in group 4 of 6, group 1 being the genes least tolerant of losing a copy. Missense variants: 455 observed, 514.18 expected, observed/expected ratio (o/e) 0.88, 90% interval 0.82 to 0.96. Synonymous variants: 164 observed, 196.26 expected, observed/expected ratio (o/e) 0.84, 90% interval 0.74 to 0.95.
Homologues: Orthologues: chimpanzee PIPOX (99% identical), macaque PIPOX (95% identical), dog PIPOX (84% identical), rabbit PIPOX (83% identical), mouse Pipox (81% identical), rat Pipox (80% identical), guinea pig PIPOX (76% identical), tropical clawed frog pipox (61% identical), zebrafish pipox (52% identical), Caenorhabditis elegans C15B12.1 (32% identical), Caenorhabditis elegans C15B12.8 (30% identical).
Diseases named in the same sentence as PIPOX in open-access papers:
PIPOX is named in the same sentence as 16 diseases in open-access papers, as found by Europe PMC text mining. Sharing a sentence is not in itself a finding about the gene and the disease. The quoted sentences say what the papers report.
breast carcinoma (4 papers, 2014 to 2023). "We analyzed the expression of GNMT, SARDH, and PIPOX in a tissue microarray of 721 breast cancer cases using immunohistochemistry (IHC)." (PMID 24884785, 2014). "sdRNA-93 derived from SNORD93 could regulate the expression of the PIPOX gene through miRNA-like silencing, contributing to the malignant phenotype of breast cancer." (PMID 36430145, 2022). "Moreover, analysis of sarcosine metabolism phenotype revealed that patients with sarcosine-high type [GNMT(+)/SARDH and PIPOX(-)] tumors had a shorter DFS than patients with other breast cancer tumor types, suggesting that sarcosine level is a prognostic factor in breast cancer." (PMID 24884785, 2014).
prostate carcinoma (3 papers, 2014 to 2021). A carcinoma that arises from epithelial cells of the prostate gland. "PIPOX, which is a sarcosine-metabolizing enzyme, is highly expressed in HER-2 type cancer but expressed at low levels in prostate cancer." (PMID 33718182, 2021). "Our earlier studies revealed that the metabolite sarcosine and its biosynthetic enzyme, glycine N-methyltransferase (GNMT) were elevated in prostate cancer, while sarcosine dehydrogenase (SARDH) and pipecolic acid oxidase (PIPOX) that metabolize sarcosine, were reduced in prostate tumors." (PMID 26140362, 2015).
breast tumors (2 papers, 2018 to 2019). "Noteworthy, it has been found that human epidermal growth factor‐2 (HER‐2)‐positive breast tumours display upregulation of sarcosine metabolism‐related enzymes (GNMT, SARDH, PIPOX)." (PMID 30628163, 2019).
sarcopenia (1 paper, 2025). Progressive decline in muscle mass due to aging which results in decreased functional capacity of muscles. "In this context, mitochondrial dysfunction–related genes such as SLC44A2, TPM3, PIPOX, and DHDPSL, which are represented among the 20 CpGs identified in our study, may play a contributory role in the pathophysiology of sarcopenia." (PMID 41297061, 2025).
cancer (2 papers, 2021 to 2025). A tumor composed of atypical neoplastic, often pleomorphic cells that invade other tissues. "To further corroborate these findings, we interrogated the RNA-seq data from the Cancer Cell Line Encyclopedia (CCLE) database and observed that SARDH, PIPOX, and GNMT, which are responsible for the conversion between glycine and sarcosine, were scarcely expressed in commonly used LUAD cell lines." (PMID 40275333, 2025).
PIPOX also shares sentences with these, for which no sentence is quoted: tumor (5 papers); psoriasis (3); Arthritis (1); autoimmune disease (1); diabetes (1); infection (1); lung carcinoma (1); prostate adenocarcinoma (1); prostate tumors (1); sleep disorder (1); viral infection (1).